PDK1 (pyruvate dehydrogenase kinase 1)
Diseases named in the same sentence as PDK1 in open-access papers (continued):
Sharing a sentence is not in itself a finding about the gene and the disease.
cancer (continued). "Pyruvate dehydrogenase kinase 1 (PDK1) blocking the trigger factor is a symbol of cancer cell metabolic changes in vitro." (PMID 38090580, 2023). "In this review, we first focus on major differences of the PAM axis between normal cells and cancer cells, and then, describe current PI3K, AKT, mTORC1/mTORC2, and PDK1 inhibitors, by summarising active and completed trials in a wide range of cancers." (PMID 37596643, 2023). "This supports an exciting therapeutic opportunity to use AKT and PDK1 inhibitors to treat MAPK4-high cancers, such as a large fraction of TNBC." (PMID 37531320, 2023). "When the WNT pathway is activated in cancers, the number of β‐catenin in the nucleus increases significantly and leads to the expression of many downstream genes, such as PDK1 and c‐myc, to promote glycolysis." (PMID 36752127, 2023). "PDK1 inhibitors have been proposed as potential cancer drugs and consistent with our findings, the PDK inhibitor AZ10219759 was reported to cause lipid accumulation in the heart with subsequent necrosis and atrial tissue degeneration." (PMID 36717164, 2023). "c-Myc is the upstream positive regulator of the Prox1-inhibited genes (GLUT1, HK2, and PDK1), identified here, as well as the Warburg effect in cancer cells." (PMID 37508533, 2023). "In cancer cells, activated Wnt signaling induces glycolysis by upregulating its downstream target genes, such as PDK1 and PARP." (PMID 37078424, 2023). "It has been reported that these genes were closely associated with cancer progression, including ENO1, PRKCB, ENO2, and PDK1." (PMID 35504868, 2022). "Taken together, our findings not only unravel a delicate feedback regulation of AKT signaling via S6K1-mediated PDK1 phosphorylation, but also highlight the potential strategy to combat mutant PDK1-driven cancers." (PMID 35318320, 2022). "These new findings suggest that the HDAC2/EZH2/miR-148a/PDK1 axis is a novel mechanism for regulating cancer development and is a potentially promising target for therapeutic options in the future." (PMID 35892859, 2022). "Most of the survival signaling molecules including PI3K, PDK1, AKT and mTOR have been associated with lipid rafts in cancer cells." (PMID 35260193, 2022). "In keeping with this finding, depletion of S6K1 in cancer cells significantly reduced PDK1 phosphorylation." (PMID 35318320, 2022). "Here, we report that the transcription factor FOXM1 activates PDK1, a glycolysis gatekeeper, and promotes glycolysis, leading to cancer progression and poor prognosis in NPC." (PMID 35656815, 2022). "In fact, PDK1 regulated the EGF-induced PLCγ1 activation of MDA-MB-231 cells in a different AKT-independent manner, and the interaction of PDK1–PLCγ1 was proved to be important for cancer cell invasion." (PMID 35159078, 2022). "In this study, pyruvate dehydrogenase kinase-1 inhibition with dichloroacetate (DCA) was explored as an alternative cancer therapy." (PMID 36142368, 2022). "Several compounds able to inhibit PDK1 function resulted in either proliferation inhibition or apoptosis of cancer cells." (PMID 36551928, 2022). "In parallel, the studies have shown an increased expression of PDK1 in cancer cells, which deactivates the PDC by phosphorylation." (PMID 36551928, 2022). "Not only does let-7C inhibit aerobic glycolysis by targeting HIF-1α, but it also found to modulate cancer progression and metabolism via inhibiting the lin28/PDK1 pathway." (PMID 36076967, 2022). "PDK1 plays a vital role in the oncogenesis and progression of human cancers and contributes to poor prognosis." (PMID 35504868, 2022). "Subsequently, IL1-β secreted by TAMs stabilizes intracellular β-catenin potentiating Wnt signaling in cancer cells via NFkB/PDK1 and glycogen synthase kinase 3-beta (GSK3β) inhibition, whereas IL-6 further amplifies inflammation within the TME." (PMID 36613445, 2022).
cancer (continued). "The PDH activity is inhibited if the enzyme is phosphorylated by its regulatory kinases PDKs and, in cancer cells, PDK1 is transcriptionally induced by HIF1α." (PMID 35163570, 2022). "Over the past three decades, numerous studies on the role of PDK1 in cancers have yielded important results that have paved the way for the development of anti-PDK1 monoclonal antibodies and specific or nonspecific PDK1 inhibitors." (PMID 35159078, 2022). "Especially, the roles of hexokinase 2 (HK2), lactate dehydrogenase A (LDHA), and pyruvate dehydrogenase kinase 1 (PDK1) have been extensively studied in various cancers." (PMID 35403278, 2022). "qPCR analysis showed high levels of ChgA, Bmi1, and glycolytic gene expression in Pdk1-mCherry+ cells compared to Pdk1-mCherry−, indicating that pPDH+ cancer cells exhibit the same cell phenotype than pPDH+ cells in the normal epithelium." (PMID 35314684, 2022). "Our study highlighted the role of PDK1 and its regulation by microRNAs in cancer metabolism and disease progression." (PMID 34298795, 2021). "Problem 1 asked teams to predict molecules that bound the RETM955T-associated cancer targets RET[M918T], BRAF, SRC, S6K, and avoided binding to MKNK1, TTK, ERK8, PDK1, and PAK3." (PMID 34520464, 2021). "Among a plethora of targetable signaling molecules, PDK1 is currently rising as a potential target for cancer therapy." (PMID 34768921, 2021). "The E3 ligase RNF126 has been found to target PDK1 for proteasomal degradation to promote cancer cell progression." (PMID 35006464, 2021). "Altered expressions of the PDK family members (PDK1–4) have been noticed in various types of malignant tumors, which are related to tumor proliferation, invasion, anti-apoptosis, and therapy resistance." (PMID 34948229, 2021). "Pyruvate dehydrogenase kinase 1 (PDK1) blockade triggers are well characterized in vitro metabolic alterations in cancer cells, including reduced glycolysis and increased glucose oxidation." (PMID 33562444, 2021). "In conclusion, baicalin represses cancer invasion by inhibiting EMT through the PDK1/AKT signaling pathway." (PMID 34868313, 2021). "Aberrant expression of Lin28 and its downstream target let-7 had previously been shown to facilitate aerobic glycolysis in cancer cells by activation of pyruvate dehydrogenase kinase 1 (PDK1)." (PMID 33804674, 2021). "Wang and Gan found that knockdown of cancer-IgG can regulate the PTP-BAS/Src/PDK1/AKT pathway and thus significantly promote cisplatin-induced apoptosis and inhibition of oral squamous cell proliferation, migration, and invasion." (PMID 34150640, 2021). "Alterations of PDK1 functions have a relevant role in pathologies such as Alzheimer’s disease, diabetes, and cancer." (PMID 35082773, 2021). "Taken together, these findings imply PDK1 can be strongly involved in modulating cancer stem cells (CSCs)." (PMID 34768921, 2021). "explore the role in CTX resistance of the mitochondrial enzyme pyruvate dehydrogenase kinase-1 (PDK1), known to allow the switching glucose metabolism toward aerobic glycolysis in cancer cells." (PMID 33718169, 2021). "Phosphoinositide-dependent protein kinase 1 (PDK1) is also one of the most important metabolic enzymes, which plays crucial roles in cancer signaling pathways, especially PI3K/Akt and Ras/MAPK pathways." (PMID 35006464, 2021). "Among a plethora of targetable signaling molecules, PDK1 is currently rising as a potential target for cancer therapy, its aberrant expression in malignancies is associated with chemoresistance." (PMID 34768921, 2021). "Previous reports have suggested that PDK1 plays an important role in cancer, and it is often modified by microRNAs or used as a drug target." (PMID 33842538, 2021). "Substantial attenuation of PDK mRNA expression was obtained in both cancer cell lines by two different shRNA vectors targeting the human PDK1 gene." (PMID 33562444, 2021).
cancer (continued). "Unquestionably, these findings are valuable in supporting the causative relationship between ARNT and ROS production but limit ARNT’s actions in ROS production to the PDK1-dependent pathway in cancer cells." (PMID 34179020, 2021). "has been reported that the expression of PDK1 is up-regulated in human PC and promotes cancer cell growth and mobility." (PMID 34221996, 2021). "For these reasons, human PDK1 is pursued as a potential drug target for cancer therapy, and a large number of inhibitors targeting human PDK1 have been developed and patented over the past 15 years." (PMID 34879056, 2021). "Analysis of the expression levels of PDK1 in different tissues showed that PDK1 was highly expressed in NSCLC cancer tissue." (PMID 34394184, 2021). "The increase in PI3K/Akt overexpression of up to 50% of all HNSCC cases suggests that inhibition of the PI3K/Akt/PDK1 signaling pathway is an effective HNSCC cancer therapy." (PMID 34452203, 2021). "Next, we analyzed the expression level of PDK1 using the cancer microarray database from Oncomine 4.028." (PMID 33446631, 2021). "SGKs, which consist of three isoforms, SGK1, SGK2, and SGK3, are critical mediators of AKT-independent signaling downstream of PDK1 and mTORC2 in cancer." (PMID 33960177, 2021). "Previous study indicated that PDK1 interfered with glucose metabolism reprogramming and mitochondrial quality control in cancer." (PMID 33029299, 2020). "It was reported that the ROS-independent ER stress pathway, which is mediated by GRP78/p-ERK/NRF2 signaling, activates PDK1 activity, and mediates the metabolic shift toward the Warburg effect in cancer-initiating cells." (PMID 32825675, 2020). "Our previous report indicated that COL11A1 enhances cell sensitivity to anti-cancer drugs via the activation of the Akt/c/EBPβ pathway in concert with attenuated PDK1 ubiquitination and degradation." (PMID 32194423, 2020). "PDK1 serves as an antiapoptotic factor in a variety of cell types, such as cancer cells, endothelial cells, and skeletal muscle cells." (PMID 32366272, 2020). "It is well known that, in many types of cancers, PDKs, especially PDK1, are overexpressed and/or its activity is increased by post-translational modifications." (PMID 32825675, 2020). "Protein kinase B (Akt), one of the most defined PDK1 targets relevant in human cancer, is involved in the regulation of cellular survival through promoting glucose metabolism by stimulating the activity of hexokinase." (PMID 33425771, 2020). "An increasing number of studies has verified that the RAF/MEK/ERK and PI3K/PDK1/Akt signaling axes are hyperactivated in various tumors, making them potential targets for new anti-cancer agents." (PMID 33072436, 2020). "In this study, we showed that IQ suppressed the growth of several types of cancer cells by inhibiting the kinase activity of PDK1 by interfering with ATP binding, subsequently dephosphorylating and activating PDHA1." (PMID 32825675, 2020). "PDK1 is highly expressed in cancer cells and promotes oncogenesis by regulating proliferation and survival." (PMID 32366272, 2020). "Activation of the upregulation of PDK1 promotes the activation of AKT-mTOR signaling in cancer cells." (PMID 32256210, 2020). "A growing amount of evidence suggests that PDK1 is upregulated in cancer cells and required for cell survival." (PMID 32366272, 2020). "Overview of PDK1–4 expression levels in different cancer types, their effect on prognosis upon up-regulation and tumorigenesis." (PMID 33384955, 2020). "Due to the suggested implication of cancer stem cell (CSCs) markers in PDK1-induced IR-resistance, we further examined if and to what extent PDK1-induced IR-resistance affects the side population (SP), which is representative of the CSCs pool in vitro." (PMID 32197467, 2020). "It was reported that the inhibition of PDK1 activity induces the production of mitochondrial ROS in cancer cells." (PMID 32825675, 2020).
cancer (continued). "PDK1 is involved in the signaling pathways that frequently altered in cancers, such as PI3K/Akt, Ras/MAPK, and Myc." (PMID 32194423, 2020). "What’s more, we have observed that decreased ubiquitination and increased stability of the metabolic related molecules, such as PDK1, NRF2, ULK1 and phosphoglycerate kinase 1, are associated with chemoresistance in various cancers." (PMID 33004065, 2020). "Activated oncogenic KRAS engages the PI3K/PDK1/AKT pathway to drive cancer initiation, progression, and maintenance." (PMID 32111094, 2020). "Further, as a key glycolytic marker PDK1 is reported to favor cell proliferation, metastases and worst prognosis, thereby making it an important therapeutic target in cancer." (PMID 33738242, 2020). "More specifically, IGF-1 has recently been shown to mediate cancer cell survival through direct modulation of the PDK1 pathway, with enhanced phosphorylation of PDK1 observed following IGF-1 stimulation." (PMID 32228485, 2020). "PKM2 also promotes the Warburg effect by activation of the HIF-1α target genes SLC2A1, LDHA, and PDK1 that facilitate the shift from oxidative phosphorylation to glycolytic metabolism to meet the nutrient demands of cancer cell proliferation." (PMID 32408513, 2020). "Suppressing PDK1 has resulted in an increase in ROS generation and induction of apoptosis in cancer cells." (PMID 32503307, 2020). "Taking into consideration the potential role of PDK1 in the development of chemoresistance in different cancer types, this evidence suggests that targeting PDK1 PH domain promotes chemosensitization." (PMID 33003448, 2020). "Hypoxia-inducible factor-1 (HIF-1), also known as a master regulator of cancer cell metabolism, regulates glycolysis under hypoxic conditions, also through the activation of PDK1." (PMID 32560271, 2020). "It has been reported that AKT is activated by phosphoinositide-dependent kinases 1 (PDK1), and then signal transduction occurs through downstream effectors such as mTOR to increase cancer cell proliferation." (PMID 33134174, 2020). "Overexpression of LIN28 has been shown to promote cancer cell proliferation, and PDK1 is critical for LIN28A/B-mediated cancer proliferation as well." (PMID 32560271, 2020). "The reprogramming of cancer metabolism through the enhancement of PDC activity via the inhibition of PDK1 increases the anticancer effects on several cancer cell lines, including NSCLC." (PMID 32825675, 2020). "A previous study has shown that Akt is a downstream target of PDK1, which phosphorylates and activates Akt in various cancers." (PMID 30717410, 2019). "Whilst PDK1 is most commonly associated with Akt signalling, it has become increasingly evident that the role of PDK1 in cancer is not limited to Akt activation." (PMID 31088502, 2019). "Further evidence of a specific role for PDK1 in cancer is provided by the observation that increased copy number of PDPK1, the gene encoding for PDK1, is frequently observed in different cancer types." (PMID 31088502, 2019). "In the present study, we observed that PDK-1 is highly expressed in NSCLC cell lines; PDK-1 depletion promoted cancer cell apoptosis and inhibited cell proliferation through Hippo–YAP/IRS2 signal pathway." (PMID 30988063, 2019). "Cancer setting where both PDK1 and Aurora A are activated are those that would benefit from the development of these dual inhibitors." (PMID 31683659, 2019). "Results from our study further supports the conclusion that PDK1 represents an important molecular target to develop novel therapeutic anti-cancer strategies." (PMID 31088502, 2019). "In various cancers, PDK-1 is upregulated, so that the pyruvate conversion into acetyl-CoA in mitochondria is decreased and the WNT-driven Warburg aerobic glycolysis induced in spite of the availability of oxygen." (PMID 31803621, 2019).
cancer (continued). "Cancer cells will undergo anoikis when they break away from where they first form, and silencing PDK1 can reduce the numbers of cancer cells in the lymph system or bloodstream by elevated anoikis resulting from upregulation of ROS." (PMID 31506552, 2019). "In this respect, it is worth mentioning that several lines of evidence now suggest that PDK1 can have a role in cancer chemoresistance and that its inhibition can promote chemosensitization." (PMID 31088502, 2019). "The diversity of substrates that can be activated by PDK1 are of high relevance in cancer signalling." (PMID 31088502, 2019). "Akt and mTORC1 pathway activation is common in many human cancers, including ccRCC and is mediated by phosphoinositide kinase 1 (PDK-1), the VHL/EGLN suppressive pathway, and the mTORC2 complex." (PMID 31519159, 2019). "Several lines of evidence now support the conclusion that PDK1 is an important potential therapeutic target in different cancer types and that its inhibition can prove beneficial to reduce growth of several cancer cell types." (PMID 31088502, 2019). "It was shown that phosphorylation of other enzymes, such as pyruvate dehydrogenase kinase 1 (PDHK1, also known as PDK1), by tyrosine kinases is involved in blocking of the mitochondrial pyruvate metabolism in cancer cells." (PMID 31847192, 2019). "Based on thiram, their further chemical efforts led to the discovery of a more potent new compound designated as bis(4-morpholinyl thiocarbonyl)-disulfide (JX06), which was identified as a selective covalent inhibitor of PDK1 in cancer cells." (PMID 34691990, 2019). "Our findings provide a novel mechanism for the tumorigenic activity of PDK1 in epithelial-derived cancer cells." (PMID 31533855, 2019). "Lastly, aspirin markedly attenuates glycolysis and cancer stem-like characteristics by suppressing both H19 and PDK1." (PMID 29106390, 2018). "Collectively, this study strongly supports the molecular network between de novo purine biosynthetic enzymes and Akt-independent PDK1 signaling pathways in cancer cells." (PMID 29668719, 2018). "Dichloroacetate (DCA) is a structural analog of pyruvate and inhibits PDK1, changing the cancer cells metabolism of cancer cells from cytoplasm-based glycolysis to mitochondria-based glucose oxidation." (PMID 29805774, 2018). "The expression levels of TNS2, Axl, IRS-1, PDK1 and Glut4 in human cancer cells were measured by Western blot and/or IP-Western blot assays." (PMID 30419905, 2018). "In this work, we reveal the spatiotemporal alterations of de novo purine biosynthetic enzymes by Akt-independent PDK1 signaling pathways in human cancer cells." (PMID 29668719, 2018). "Several studies showed that PDK1 is overexpressed in particular cancers and activates growth and survival of cancer cells independent of Akt signaling." (PMID 30126855, 2018). "Cancer cells can evade such a response, as they activate pyruvate dehydrogenase kinase 1 (PDK1) or inhibit pyruvate dehydrogenase phosphatase catalytic subunit 2 (PDP2), resulting in limited pyruvate utilization by mitochondria and reduced ROS production." (PMID 29219147, 2018). "Recently, studies have shown that the HIF-1A induced expression of PDK1 limits the oxidation of pyruvate to acetyl-CoA by inhibiting the pyruvate dehydrogenase complex in cancers of the breast and kidney." (PMID 30018740, 2018). "The results of our present study suggest that knockdown of Axl expression reduces glucose uptake and that Axl is related to high expression of glucose metabolism molecules, IRS-1, Glut4 and PDK1 in cancer tissues." (PMID 30419905, 2018). "Let-7 is commonly downregulated in many cancers, which leads to the upregulation of its direct target, PDK1, and facilitates aerobic glycolysis." (PMID 29662084, 2018). "Rapamycin has been reported to induce feedback activation of Akt in various cancer cells through increased phosphorylation at S473 by mTORC2 and at T308 by PDK1 [6, 16 and 17]." (PMID 28938574, 2017).